BCL2 (BCL2 apoptosis regulator)
Diseases named in the same sentence as BCL2 in open-access papers (continued):
Sharing a sentence is not in itself a finding about the gene and the disease.
tumor (continued). "The results demonstrated that inhibition of tumor growth was related with the decrease of Bcl-2 protein expression and the increase of the BAX and Caspase-3 protein expression." (PMID 28514759, 2017). "In H22-bearing mice, APS produce a tumor inhibition rate of 59.01%, increase the spleen and thymus indexes, and promote cell apoptosis by increasing Bax and decreasing Bcl-2 expression, improve the phagocytotic function of macrophages." (PMID 29344421, 2017). "Consistent with in vitro results, western blot analyses of tumor tissues revealed Bcl-2 and p-AktThr308 downregulation in R7-treated mice compared with controls." (PMID 29312623, 2017). "Whereas, co-delivery of lipo-PTX/Bcl-2 siRNA showed significant (p < 0.001) inhibition of tumor growth compared with other experimental groups." (PMID 27786239, 2016). "In the present investigation, we have designed a novel pH-sensitive liposomal delivery system to co-deliver PTX and Bcl-2 siRNA into the tumor cells and mice models." (PMID 27786239, 2016). "Upregulation of non-targeted anti-apoptotic BCL-2 family proteins taking over the function of BCL-2 has earlier been described as one of the key mechanisms of tumor resistance to BCL-2 inhibitors including ABT199." (PMID 27056887, 2016). "Functioning as a tumor suppressor, miR-15a targets oncogene BCL2, and within tumor cells miR-15a itself is down regulated." (PMID 27059462, 2016). "Western blot revealed that TPL induced apoptotic protein (Bax) and decreased anti-apoptotic protein (Bcl-2) expression in xenograft tumor tissues." (PMID 27999372, 2016). "For example, anti‐apoptotic Bcl‐2 protein also inhibits autophagy by inhibiting beclin; an autophagy gene initially identified as tumour suppressor." (PMID 26648178, 2016). "ER and PR significantly decreased in all tumours by 6 months (p < 0.001), with some declines in ER (serine 118) phosphorylation and Bcl‐2 (p = 0.007)." (PMID 26178788, 2016). "The overexpression of Bcl-2 is closely related to chemotherapy drug resistance, and the suppression of Bcl-2 has been shown to increase the sensitivity of tumour cells to chemotherapeutical drugs." (PMID 27601167, 2016). "This selective translation is mediated by the overexpression of eIF4E-BPs and eIF4G and is particularly advantageous for cancer cells as VEGF, FGF-2, HIF1α, and Bcl-2 are all significant factors in promoting tumor growth and survival." (PMID 28083147, 2016). "Synergistic rational anticancer combined protocols are presented depending on the tumour cell background, like resistance to individual treatments, BRAF mutation or BCL-2 overexpression." (PMID 27520705, 2016). "We also examined the expression of Bcl-2 and survivin, since both are central regulators of apoptosis and contribute to tumor progression." (PMID 27095571, 2016). "We also analyzed the expression of apoptosis-related proteins Bcl-2 and Bax in tumor tissue samples from each group by immunohistochemistry and Western blot." (PMID 26974964, 2016). "The miR-15b/miR-16-2 cluster, which is located in 3q25, has also been reported to act in tumor suppression by targeting BCL2, BM1, CCND1 and SUZ12." (PMID 27195958, 2016). "Sal further reduced the expressions of STAT3-modulated Bcl-2 and Bcl-xL both at mRNA and protein levels, and increased the levels of pro-caspase-3 all known to promote tumor survival and tumor growth." (PMID 27058891, 2016). "It has been found to be highly expressed in tumor cells and be one of the crucial regulators of cell proliferation and apoptosis by targeting cell cycle proteins and Bcl-2 protein, suggesting the potential importance of miR-15b in cancers." (PMID 26931521, 2016).
tumor (continued). "IGF-1, through the activation of key signaling pathways, enhancing the expression of pro-survival factors, such as Bcl2, Bcl-X(L) and Survivin, and favoring DNA damage repair, is a key target for enhancing the response of tumor cells to drugs." (PMID 27764776, 2016). "Together these results suggest that Apc−/− cells are dependent on Bcl-2 for survival and clonogenic expansion, both during tumour initiation as well as in established adenomatous tissue." (PMID 26956214, 2016). "MiRNA hsa-miR-195 was found to be downregulated in several cancers and is believed to function as a tumor suppressor by targeting BCL2." (PMID 27144577, 2016). "Suppressing the expression of GLI1 inhibited the overexpression of Bcl-2 and the proliferation of tumour cells while simultaneously promoting cell apoptosis." (PMID 27601167, 2016). "The quantitative analysis of Bcl2-positive cells revealed a significant (P < 0.001) decrease in immunopositive cells in tumor sections from rats received medium or high dose of PE." (PMID 26699876, 2016). "BH3 mimetic compounds induce tumor cell death through targeted inhibition of anti-apoptotic BCL2 proteins." (PMID 26910119, 2016). "Increase in the Bax/Bcl-2 ratio in tumor cells treated with plasma is another finding which is of great importance." (PMID 27383714, 2016). "Tumor apoptosis related protein bcl-2, bax and caspase 3 expression after different treatment was evaluated by western blot assay." (PMID 27793127, 2016). "We also investigated highly the immunochemical expression of CXCR4, MIF and Bcl-2 in HCT-116/OxR tumor sections." (PMID 27668882, 2016). "We subsequently measured the expression levels of BAX, Bcl-2, and survivin in all tumor tissues using Western blot." (PMID 27248325, 2016). "At the same time, detection of BCL-2 protein expression in xenograft tumor tissues also showed the strongest positivity in the cytoplasm of tumor cells from the control groups, and a marked decrease in response to DDP treatment." (PMID 27986075, 2016). "In fact, a decrease in the bax/bcl-2 ratio is commonly observed in various tumors, and closely correlates with the inhibition of cell apoptosis, insusceptibility to undergo apoptosis, tumor recurrence and patients’ poor prognosis." (PMID 27886059, 2016). "As Bcl-2 family members are key regulators of apoptosis, the expressions of anti-apoptotic Bcl-2 and pro-apoptotic Bax were measured in tumor tissues of mice treated with either Erdr1 or the vehicle." (PMID 26784177, 2016). "At the same time, DOX/RES-loaded NPS induced the tumor cells aptotosis by decreasing BCL-2 expression and increasing Bax and caspase-3 expression in vivo." (PMID 27731405, 2016). "The regulation of pro- and anti-apoptotic proteins in imiquimod treated tumour cells has been well established, with several studies measuring changes to BCL2, MCL1, A20 and Noxa after treatment." (PMID 27936237, 2016). "The polyphenolic compound gossypol evokes Bak/Bax-independent apoptosis and inhibits Bcl-2-overexpressing tumor growth." (PMID 26758417, 2016). "In the 3q27 band are found the THPO gene, involved in the cellular development process, and the BCL2 tumor suppressor gene." (PMID 27479010, 2016). "In the present study, detection of BCL-2 protein expression in xenograft tumor tissues showed that the expression of BCL-2 was weakest in ST6Gal-I-shRNA + DDP group, and thus the increased apoptosis in HeLa cells." (PMID 27986075, 2016). "To further investigate C12-initiated apoptosis in tumor cells, we studied the involvement of Bcl-2 in two key events of MOMP: depolarization of mitochondrial membrane potential (Δψmito) and cytochrome c release." (PMID 26758417, 2016). "The Bax/Bcl-2 ratio in the tumours treated with the honey-Aloe vera combination was raised, the authors concluding that honey and Aloe vera can modulate tumour growth by increasing the susceptibility to apoptosis." (PMID 28933410, 2016).
tumor (continued). "Further studies have shown that miR-15a and miR-16-1 act as putative tumor suppressors by targeting BCL2, BMI1 CCND1, MCL1 and WNT3A in CLL, melanoma, as well as colon, bladder, ovarian and prostate cancers." (PMID 27195958, 2016). "High expression of Bcl-2 was reported to be responsible for the apoptosis or autopahgy resistance induced by IFN-γ in human tumor-derived endothelial cells or human lung epithelial A549 cells." (PMID 26758620, 2016). "hPEPD-G278D also up regulated BAX, down regulated BCL-2 and activated caspase-3 in the tumor tissues, which is consistent with marked tumor regression upon hPEPD-G278D treatment." (PMID 27286447, 2016). "Tumour cells often evade apoptosis by overexpressing anti-apoptotic proteins, such as Bcl-2, which give them a survival advantage." (PMID 27924151, 2016). "The authors argued that Bcl-2/Mcl-1 tumor cell profiles would indicate the benefit of ABT-737 therapy and should be incorporated to guide its use." (PMID 27119356, 2016). "In order to examine the mechanism underlying the inhibition of tumor growth by Huaier extract and TAM in vivo, we measured Lc3b, Bcl-2, and Ki67 protein levels using immunohistochemical staining." (PMID 27027343, 2016). "For example, miR-21 has been repeatedly reported to facilitate tumor progression through targeting assorted tumor-suppressors, such as Bcl-2, PDCD4 and PTEN." (PMID 27006642, 2016). "In fact, tumor proliferation, expressed as the ratio of Bcl-2 mRNA copy number to that of Bax, was found to be inversely proportional to the decrease of L3 gene expression and increased with tumor grade, as previously reported." (PMID 27835895, 2016). "Such tumours with a pMAPK decrease by 6 months (n = 16) also showed significant decline in pEGFRm (p = 0.013), Bcl‐2 (p = 0.031) and Ki67 (p = 0.003)." (PMID 26178788, 2016). "For example, although IgM+ lymphoproliferation including LPL-like neoplasia was fully penetrant in BCL2+IL6+AID− mice, serum IgM levels were low compared with patients with WM and serum IgM spikes were rarely seen." (PMID 27813533, 2016). "Having identified Bcl-2 as a critical facilitator of tumour formation, we wished to formally confirm that the consequences of impaired Bcl-2 function are specific for Apc deficient cells." (PMID 26956214, 2016). "Accordingly, apoptosis-regulating factors including anti-apoptotic marker Bcl-2 and pro-apoptotic marker Bax in the tumor tissues were examined." (PMID 26784177, 2016). "The mixture increased apoptosis of tumor cells as indicated by an increased ratio of Bax/Bcl-2 and downstream activation of caspase 7 along with increased cleavage of its substrate PARP1." (PMID 27151407, 2016). "The anti-apoptotic genes, such as Bcl-2 and Bcl-XL, increased their expression in tumor-bearing rats as compared to normal rats, whereas tumor-bearing rats treated with 1,3-BPMU had downregulated Bcl-2 and Bcl-XL expressions as compared to tumor-bearing rats." (PMID 27187346, 2016). "Analysis of tumours isolated on day 5 of the treatment regimen confirmed the activation of mitochondrial apoptotic signalling with a decrease in both pro-apoptotic Bcl2 proteins and IAP proteins, as well as an increase in cleaved caspase 3 proteins." (PMID 27384486, 2016). "Immunoblot analysis showed that elevated expression of La protein correlates with increased Bcl2 protein expression in four HNSCC tumor tissues lysates when compared to three normal tongue tissue lysates." (PMID 27105491, 2016). "Bcl-2 expression was shown to provide with unprecedented protective power versus tumor recurrence, candidating the combined assessment of these IHC parameters for use in clinical settings." (PMID 27538498, 2016).
tumor (continued). "Further investigations have revealed that it can alter mitochondrial Bax-Bcl2 balance to suppress tumor cell adaptation to hypoxia." (PMID 27149165, 2016). "A clear knock down of Bcl-2 gene was observed at both mRNA and protein levels in tumor samples administered with liposome formulations." (PMID 27786239, 2016). "This study showed that baicalein obviously inhibited tumor growth and induced apoptosis in U14 cervical cancer cells by upregulating the expression of Bax and downregulating the level of Bcl-2." (PMID 27735841, 2016). "The cluster of miR-15a/miR16-1 was reported to target Bcl-2, CCND1 (encoding cyclin D1) and WNT3A, leading to tumor cell growth arrest and apoptosis." (PMID 27151407, 2016). "MiR-195 functions as a tumor suppressor miRNA by targeting several genes involved in cell cycle acceleration and anti-apoptotic factors including BCL-2." (PMID 27144561, 2016). "The tumor suppressor function of miR-17/92 is mostly explained through targeting pro-survival proteins BCL2, STAT5 and JAK2." (PMID 27179712, 2016). "When evaluated in mice bearing human xenograft AML tumors, Tf-LPN-G3139 suppressed tumor growth by ~60% at the end of treatment period, accompanied by remarkable pharmacological effect of Bcl-2 inhibition in tumor." (PMID 27034925, 2016). "Above results indicated that ACDB treatment strongly suppressed JJ012 xenograft tumor growth in vivo through regulation Bax, Bcl-2, GRP-94, and calpain I signaling." (PMID 27835579, 2016). "Pharmacological inhibition of anti-apoptotic Bcl-2 proteins in cancer has emerged as a major strategy to induce apoptosis and tumour regression." (PMID 26785948, 2016). "Tumor cells often increase the expression and/or activity of anti-apoptotic Bcl-2 members to bind to and sequester stress-activated BH3 proteins to prevent their binding to Bax and or Bak to inhibit apoptosis." (PMID 26874859, 2016). "Consistent with the notion that miR-130a can act as a tumor suppressor by targeting BCL2 and MCL-1 expression, lower expression of miR-130a is associated with poor prognosis as indicated by shorter overall survival and treatment-free survival in CML patients." (PMID 27179712, 2016). "For example, BCL2-associated agonist of cell death (BAD) functions as a shared target of Akt and ERK signaling in phosphatase and tensin homolog (PTEN) deficient tumor cells." (PMID 26848623, 2016). "Upon further investigation, this differential sensitivity was found to correlate with elevated expression of BCLxL compared to BCL2 in MiaPaCa2 tumor cells similar to other cancers of epithelial origin." (PMID 27359113, 2016). "Jin’s group have observed that hypoxia is able to prevent serum deprivation-induced apoptosis of tumor cells by decreasing the Bax/Bcl-2 ratio and inhibiting the caspase 3 activity." (PMID 27658583, 2016). "We showed that two therapeutic agents-loaded in pH-responsive liposomal formulation (PTX/Bcl-2 siRNA) accumulated much more effectively in tumor tissue." (PMID 27786239, 2016). "Previous work in CLL has demonstrated the tumor suppressor activity of the miR-15a/16-1 cluster is dependent on repression of BCL2." (PMID 27195958, 2016). "It has been reported that miR-206 activates apoptosis and inhibits tumor cell proliferation, migration and colony formation through targeting c-Met and Bcl-2." (PMID 26919096, 2016). "Next we detected the phosphorylation of ERK1/2 and JNK, Cyclin D1, Bcl-2, Caspase 3 and Bax in tumor tissue." (PMID 26901856, 2016). "This pH-sensitive liposomal nanocarrier effectively delivers anti-cancer drug (Paclitaxel; PTX) and siRNA (Bcl-2), and significantly inhibits cell proliferation and reduces tumor growth." (PMID 27786239, 2016).
tumor (continued). "Overall, our study reveals that C12 inhibits tumor growth in animals as a single agent, through inducing a unique Bcl-2 protein-independent and PON2-mediated apoptotic cascade in tumors." (PMID 26758417, 2016). "In conclusion, we found that miR-139-5p targeted the BCL2 pathway to reduce tumour metastasis and drug sensitivity in CRC." (PMID 27244080, 2016). "Specifically, miR-15a and miR-16-1 directly regulate BCL2, which is an anti-apoptotic oncogene, and hence act as tumor suppressors by inducing apoptosis." (PMID 27195958, 2016). "Solid tumors are more heterogeneous, often having different Bcl-2 anti-apoptotic protein dependence patterns even within the same tumor type." (PMID 26874859, 2016). "For instance, overexpression of the antiapoptotic Bcl-2 genes is frequently observed in solid human tumours." (PMID 26936767, 2016). "Tumor apoptosis related proteins, bcl-2, bax and caspase 3, were evaluated by western blot analysis." (PMID 27793127, 2016). "Increase in Connexin 43 expression promoted tumor cell apoptosis and downregulated Bcl-2 expression." (PMID 27623212, 2016). "Up-regulation of Bax and down-regulation of Bcl-2 in S-180 tumor tissues were respectively observed." (PMID 27353254, 2016). "RT–PCR and immunoblot analysis confirmed that the expression level of miR-125a, STAT3, p-STAT3 (Tyr705), Bcl-2 and Bcl-xL in HeLa/PR cells from the representative tumor mass." (PMID 26878391, 2016). "Many research reports that, in several tumour cell types, the forced overexpression of Bcl-2 has been considered resistance to chemotherapeutic agents." (PMID 27601167, 2016). "Increased cell proliferation and inhibition of cell apoptosis cause tumor and cancer, whereas in cancer-bearing rats treated with 1,3-BPMU, Bcl-2 and Bcl-XL mRNA transcripts were significantly downregulated as compared to cancer-bearing rats." (PMID 27187346, 2016). "In tumor cells, activation of Stat3 involve in regulation of anti-apoptotic genes and cell cycle regulators, such as Bcl-xL, Bcl-2, Cyclin D1 and PCNA." (PMID 27563884, 2016). "Decreased B-cell lymphoma 2 (Bcl-2) and increased bcl-2 like protein 4 (Bax) expression were detected on tumor tissues from the affected mouse." (PMID 27941650, 2016). "Previous studies have confirmed that STAT3 alterations affect Bcl-2 and Bax protein expression and induce inflammation and apoptosis in many types of tumor cells." (PMID 25946003, 2015). "We found that the major factor of the tumor immunophenotype variation was characterized by a strong inverse relation between the expression of ER, PR, AR along with anti-apoptotic marker BCL2, on one side, and Ki67 and HIF-1α, on the other side." (PMID 26512778, 2015). "We further demonstrated that both Bax and Bcl-2 expression in BL-EI001-treated tumor samples were consistent with immunohistochemistry results and caspase cascade activation." (PMID 25742792, 2015). "Another Chinese herbal compound, xihuangwan, induces tumor cell apoptosis by decreasing the Bcl-2 transcription level and has an inhibitory effect on H22 tumors." (PMID 26042820, 2015). "BCL-2 protein is known to regulate apoptosis and normally results in the promotion of tumor cell survival by blocking programmed cell death." (PMID 26090392, 2015). "BCL2 expression increased over BAX expression with increasing malignancy of the tumor from TC to SCLC." (PMID 26008974, 2015). "We further observed in this study that endothelial cells expressing Bcl-2 showed significantly higher tumor cell binding and this endothelial-tumor cell binding was predominantly mediated via the E-selectin." (PMID 26509633, 2015).